HR (HR lysine demethylase and nuclear receptor corepressor)
Diseases named in the same sentence as HR in open-access papers (continued):
Sharing a sentence is not in itself a finding about the gene and the disease.
breast cancer (continued). "Across EU5, 226 physicians provided data on 781 women with HR+/HER2− advanced breast cancer taking their first ET-based regimen for advanced disease, of whom 252 provided PRO data." (PMID 32894087, 2020). "Of the 290 patients, 47.2% (137/290) had TNBC, 31.3% (91/290) had HR+/HER2−, 6.9% (20/290) had HR+/HER2+, and 12.4% (36/290) had HR−/HER2+ breast cancer." (PMID 32695676, 2020). "We report the genetic evolution of two HR+/HER2− breast cancer patients who presented with de novo metastatic disease." (PMID 32221288, 2020). "Overall, 226 physicians across the EU5 provided data on the analysis cohort (i.e., patients with HR+/HER2− advanced breast cancer currently receiving an ET-based regimen as initial treatment for advanced disease)." (PMID 32894087, 2020). "The RENATA study is the first prospective experience utilising palbociclib in daily clinical practice in the Latin American population with HR+/HER2− advanced-stage breast cancer diagnosis." (PMID 32582373, 2020). "Endocrine therapy (ET)-based regimens are the mainstay of treatment for patients with hormone receptor-positive/human epidermal growth factor receptor 2-negative (HR+/HER2−) advanced breast cancer." (PMID 32894087, 2020). "Several PI3K inhibitors have been developed and one, alpelisib, was recently approved for use in PIK3CA‐mutated, HR+, HER2‐negative advanced breast cancer." (PMID 32697890, 2020). "The characteristics of this subset of women were similar to the overall EU5 sample with HR+/HER2− advanced breast cancer currently receiving their initial ET-based regimen." (PMID 32894087, 2020). "We conducted a multi-center retrospective cohort analysis of HR+/HER2+ stage IV breast cancer patients, explicitly evaluating treatment utilization and overall survival among patients treated with hormonal therapy or chemotherapy." (PMID 31792304, 2019). "The success rates according to breast cancer subtype were 3.6% for HR+/HER2−, 21.4% for HR+/HER2+, 21.9% for HR−/HER2+, and 22.5% for triple-negative breast cancer (TNBC)." (PMID 31018595, 2019). "One-on-one concept elicitation interviews were conducted with 15 patients with HR+/HER2- advanced breast cancer." (PMID 30734110, 2019). "In order to evaluate treatment benefits from the patient perspective, it is necessary to understand the most important and relevant aspects of the HR+/HER2- advanced breast cancer experience." (PMID 30734110, 2019). "The Phase III MONALEESA-2 trial (NCT01958021) enrolled 668 postmenopausal HR+/HER2- sub-type breast cancer patients, among them 295 patients were over 65 years old." (PMID 31777590, 2019). "We believe that the management of patients with HR+/HER2- advanced breast cancer will focus on overcoming ET resistance." (PMID 29901634, 2018). "Buparlisib, a pan-class I PI3K inhibitor, in combination with fulvestrant has been investigated in two randomized placebo-controlled phase 3 trials (BELLE-2 and BELLE-3 trial) in pretreated postmenopausal women with HR+/HER2− advanced breast cancer." (PMID 30595753, 2018). "Recently, Freedman et Al brilliantly reviewed the efficacy and safety in older patient subsets in studies of endocrine monotherapy versus combination therapy in patients with HR+/HER2- advanced breast cancer." (PMID 30159129, 2018). "Among PI3Ka-mutated human breast cancer cell lines, we chose four cancer cell lines representative of each breast cancer subtype: BT474 cells (HER2/HR+), MCF7 (HR+), KPL4 (HER2+) and SUM159 (TNBC)." (PMID 29100327, 2017). "In this study, three breast cancer cell lines with different molecular subtypes were used: MCF-7(HR+/HER2−), SKBR-3(HR−/HER2+) and MDA-MB-231(HR−/HER2−)." (PMID 27624978, 2016). "Palbociclib, ribociclib, and abemaciclib are among the Cyclin-dependent kinase 4 and 6 (CDK4/6) inhibitors that have become an innovative family of targeted therapy for hormone receptor-positive, Human Epidermal Growth factor receptor 2 (HR+/HER2-) breast cancer." (PMID 41930171, 2026).
breast cancer (continued). "In addition, combination of PI3K/mTOR inhibitor Gedatolisib plus Palbociclib and endocrine therapy in women with HR+/HER2-negative advanced breast cancer was well tolerated with an acceptable safety profile." (PMID 40260297, 2025). "A total of 127 postmenopausal patients with HR+/HER2− breast cancer were included in the study." (PMID 40723203, 2025). "The development of novel immunotherapies for HR+/HER2− breast cancer is incredibly challenging." (PMID 41465595, 2025). "Trastuzumab Deruxtecan, an antibody-drug conjugate (ADC) consisting of a humanized anti-ERBB2 (HER2) monoclonal antibody linked to the topoisomerase I inhibitor Deruxtecan, represents a novel therapeutic option for patients with advanced hormone receptor-positive (HR+, e.g., ER+) breast cancer." (PMID 39991577, 2025). "The data suggested that leuprorelin (Boennuokang®) plus endocrine therapy could achieve a favorable prognosis in premenopausal women with HR+/HER2− breast cancer." (PMID 40678728, 2025). "Furthermore, increased CDK9 mRNA expression in plasma-derived exosomes from HR+/HER2-breast cancer patients treated with palbociclib plus hormonal therapy correlates with clinical resistance." (PMID 40949156, 2025). "Here we report the first case in literature of a patient with HR+/HER2+ early-stage breast cancer experiencing a type I KS following paclitaxel infusion and the role of genomics to disentangle such a complex therapeutic scenario and re-define the oncological management." (PMID 40199689, 2025). "After 2010, however, a countertrend emerged among patients with HR+/HER2- breast cancer." (PMID 41338056, 2025). "In conclusion, leuprorelin (Boennuokang®) combined with endocrine therapy effectively suppresses gonadotropins and E2 to postmenopausal levels and demonstrates encouraging long-term PFS rates with a favorable safety profile in premenopausal women with HR+/HER2− breast cancer." (PMID 40678728, 2025). "Both participants had HR+/HER2− breast cancer and were receiving Q1/3W dosing." (PMID 40762544, 2025). "In summary, our study revealed the stimulatory effects of XBP1s on cell proliferation, cell cycle progression from G1 to S phase, and the development of cross‐resistance to palbociclib and fulvestrant by modulating the SND1/E2F1 axis in HR+/HER2− breast cancer." (PMID 40940685, 2025). "Importantly, the study reflects real-world clinical practice in a tertiary oncology center, offering insights relevant to everyday management of postmenopausal women with HR+/HER2− early breast cancer." (PMID 40723203, 2025). "This integrative approach provides insights into breast cancer biology and highlights C. urens as a promising candidate for developing targeted treatments, especially for the HR+/HER2-subtype, potentially enhancing therapeutic outcomes in challenging cancer cases." (PMID 40081286, 2025). "A current clinical study (NCT05766410) is comparing the immunomodulatory effects of palbociclib, ribociclib and abemaciclib each combined with letrozole in the neoadjuvant setting for HR+/HER2− early-stage breast cancer; the trial is actively recruiting and its results are eagerly awaited." (PMID 41463246, 2025). "However, the follow-up duration in our series is short, limiting our ability to demonstrate that HR+/HER2- breast cancer patients with high KPNA2 but low FOXM1 mRNA levels exhibit significantly better survival outcomes beyond the TCGA cohorts." (PMID 40002266, 2025). "RIGHT Choice was a randomized phase 2 clinical trial of ribociclib plus letrozole plus goserelin that explored the efficacy and safety of this combination versus chemotherapy in pre-/perimenopausal women with clinically aggressive HR+/HER2− advanced breast cancer." (PMID 41479780, 2025). "Targeting ADK fusions represents a promising therapeutic strategy for HR+/HER2‒ breast cancer." (PMID 41213951, 2025). "Baseline characteristics of 106 NAC patients with HR+/HER2- breast cancer." (PMID 40936892, 2025).
breast cancer (continued). "The phase III clinical trial (NCT01958021) and (NCT02278120) demonstrated that ribociclib and letrozole combination therapy can improve the progression-free survival (PFS) of postmenopausal and premenopausal women with HR+/HER2-negative breast cancer, respectively." (PMID 38894873, 2024). "This study was a multicenter retrospective evaluation of the electronic health records of 212 patients with HR + /HER2− advanced breast cancer in Andalusia, 175 (82.5%) patients using CDK4/6 inhibitors and 37 (17.5%) patients using endocrine therapy without CDK4/6 inhibitors (control group)." (PMID 38831191, 2024). "HR+/HER2- subtypes of breast cancer are the most common and exhibit significant heterogeneity." (PMID 39247184, 2024). "Moreover, the subgroup analyses in the 2 large trials indicated that pCR rate varied from 5% to 50% in different subgroups, suggesting that HR+/HER2– breast cancer possessed a highly heterogeneous tumor immune microenvironment." (PMID 39531335, 2024). "The study demonstrated that this combination significantly improved PFS (palbociclib vs placebo group: 31.8 vs 22.0 months) and ORR (palbociclib vs placebo group: 68.3% vs 42.2%), further supporting its effectiveness in HR + /HER2- advanced breast cancer patients." (PMID 38409585, 2024). "In addition, a study confirmed that acute kidney injury in six biopsies-confirmed patients with HR+/HER2-breast cancer was directly related to CDK4/6 inhibitors." (PMID 39640578, 2024). "Consequently, data are lacking on the optimal neoadjuvant systemic treatment of patients with HR+/HER2+ breast cancer who are unfit for the combination of chemotherapy and anti-HER2 therapy." (PMID 39766087, 2024). "Approximately 70% of newly diagnosed breast cancers are of the HR+/HER2- subtype." (PMID 38817360, 2024). "HR+/HER2-breast cancer is the most common type, accounting for about 70% of all cases." (PMID 39684756, 2024). "Gedatolisib is currently being evaluated in a Phase 1/2 clinical trial in combination with darolutamide in patients with mCRPC previously treated with an AR inhibitor, and in a Phase 3 clinical trial in combination with palbociclib and fulvestrant in patients with HR+/HER2− advanced breast cancer." (PMID 39092562, 2024). "The patients were divided into four types according to the HR and HER2 status of preoperative biopsy: 107 patients (42.1%) had HR + /HER2- breast cancer, 46 patients (18.1%) had HR + /HER2 + breast cancer, patients (20.9%) had HR-/HER2 + breast cancer, and 48 patients (18.9%) had TNBC." (PMID 38166846, 2024). "One reason for this lies in the biology of HR+/HER2- breast cancers." (PMID 39247184, 2024). "In summary, we revealed 2 immunologically distinct subtypes in terms of immune infiltration, PD-L1 expression, and response to immunotherapy with comparable TMB and clinical features, indicating that HR+/HER2– breast cancer possessed a highly heterogeneous immune environment." (PMID 39531335, 2024). "Between 2008 and 2019, 15,736 patients were diagnosed with HR+/HER2+ breast cancer." (PMID 39766087, 2024). "Several Trop-2-targeted ADCs, such as Sacituzumab Govitecan (SG) and Datopotamab Deruxtecan (Dato-DXd), have demonstrated significant antitumor activity in clinical trials for both triple-negative breast cancer (TNBC) and hormone receptor-positive/HER2-negative (HR+/HER2-) breast cancer." (PMID 39555080, 2024). "In conclusion, the in‐depth analysis of the SOFT study suggests that HER2 status and trastuzumab adjuvant treatment influence the benefit of OFS treatment, and it is necessary to conduct research on premenopausal patients with HR+/HER2+ early‐stage breast cancer who received trastuzumab." (PMID 38185807, 2024). "The predominant breast cancer subtype was HR+/HER2‐ (72.0%) and tumors of ductal origin (75.3%)." (PMID 39548728, 2024).
breast cancer (continued). "The question is whether the added toxicity of anti-HER2 is justified in the neoadjuvant setting for patients with HR+/HER2+ breast cancer who are unfit for chemotherapy." (PMID 39766087, 2024). "Therefore, prospective studies in more centers and larger samples of HR+/HER2+ breast cancer patients are needed in the future." (PMID 38185807, 2024). "However, the therapeutic exploration of ICIs in HR+/HER2– breast cancer is still in its early stages." (PMID 39531335, 2024). "Although HR+/HER2- breast cancer is less responsive to neoadjuvant therapy than other breast cancer subtypes and PCR is difficult to obtain, it can still benefit from this approach, particularly in terms of improved objective tumour remission and breast conservation rates." (PMID 39247184, 2024). "One of the most common subtypes (20–25% of all breast cancers) is HR+/HER2- breast cancer." (PMID 36900131, 2023). "Among the three drugs, palbociclib and abemaciclib have been approved for clinical use in Japan, with palbociclib receiving its first regulatory approval for unresectable or recurrent breast cancer in 2017 and abemaciclib receiving approval 1 year later for advanced HR+, HER2− breast cancer." (PMID 36414795, 2023). "We conducted a retrospective, observational, monocentric study including 39 consecutive patients with HR+/HER2- advanced breast cancer treated with abemaciclib and endocrine therapy at our institution from July 2019 to May 2021." (PMID 36902563, 2023). "This is of particular interest as nearly 3⁄4 of all breast cancers are HR+, HER2-." (PMID 37637072, 2023). "We further analyzed the changes in antibody titers in patients with different molecular subtypes of breast cancer, including 18 cases of the HR+/Her2+ subtype, 48 cases of the HR+/Her2– subtype, 18 cases of the HR–/Her2+ subtype, and 10 cases of the HR–/Her2– subtype." (PMID 36817926, 2023). "A majority of patients identified within this study had HR+/HER2- breast cancer." (PMID 37504365, 2023). "The second line may be the optimal setting for patients with HR+/HER2− advanced breast cancer to receive CDK4/6is, according to findings from the phase III SONIA trial presented at the 2023 ASCO Annual Meeting." (PMID 37759823, 2023). "Compared to patients with TNBC who were also included in OlympiA, far fewer breast cancer patients with early-stage, high-risk, HR+/HER2−, and gBRCAm receive olaparib due to a lack of comprehensive testing." (PMID 37623478, 2023). "Endocrine therapy is an important subset of systemic therapy for HR + /HER2- breast cancer." (PMID 36870942, 2023). "Notably, breast cancer is a heterogeneous disease with distinct molecular subtypes such as hormone receptor-positive (HR+), human epidermal growth factor receptor 2-positive (HER2+), and triple-negative breast cancer (TNBC)." (PMID 37954074, 2023). "Breast cancer (BC) is the most common cancer diagnosis (12% of total; 25% in women) and the leading cause of cancer death in women worldwide, with the majority of cases attributable to the hormone receptor-positive and HER2-negative (HR+/HER2-) subtype." (PMID 37511178, 2023). "Elacestrant may be an option for patients with HR+/HER2- breast cancer whose disease progressed on fulvestrant in the metastatic setting." (PMID 37318638, 2023). "However, in this review we stay focused on molecular resistance to the treatment of HR+/HER2- breast cancer." (PMID 36900131, 2023). "However, intrinsic or acquired resistance of HR+/HER2- metastatic breast cancer to clinically approved CDK4/6 inhibitors are responsible for disease progression in the majority of patients." (PMID 35938171, 2022). "Moreover, to date, abemaciclib is the first FDA-approved CDK4 & 6i approved for the adjuvant treatment of HR+, HER2–, node-positive, early breast cancer (EBC) at high risk of recurrence and a Ki-67 score ≥20%." (PMID 35813283, 2022).
breast cancer (continued). "However, it is still worth noting that since the HR+/HER2- subtype accounts for the highest proportion (approximately 70%) of breast cancer, the total number of patients who finally achieved axillary pCR after NST is not small." (PMID 36506067, 2022). "Ki-67 score could become a useful prognostic marker to guide treatment decision-making in patients with HR+, HER2− early breast cancers with intermediate risk of disease recurrence." (PMID 35524219, 2022). "We retrospectively investigated in women treated with fulvestrant for HR+/HER2 negative advanced breast cancer clinical, pathological and molecular features associated with long-term benefit from treatment defined as being progression-free at 18 months." (PMID 35896637, 2022). "Biological processes revealed in the HER2+ and TN subtypes included “vascular endothelial cell proliferation” and “stress granule assembly”, while the HER2+ and HR+ subtypes showed a dysregulation of “Titin binding”, all of which are involved in tumorigenesis of breast cancers." (PMID 34088263, 2021). "Current Japanese Breast Cancer Society Clinical Practice guidelines recommend a CDK4/6 inhibitor plus an aromatase inhibitor as a first-line endocrine therapy for postmenopausal patients with HR+/HER2‒ ABC." (PMID 34698970, 2021). "These four patients had HR+/HER2+ breast cancer and remained progression free for 67 weeks or more, with one patient still on study after 131 weeks on treatment as of May 2020." (PMID 34169393, 2021). "The majority of patients on this trial had HR+/HER2+ breast cancer." (PMID 34169393, 2021). "Based on their receptor status, the six breast cancer cell lines were divided into three subtypes: hormone receptor positive (HR+: MCF7), human epidermal growth receptor positive (HER2+: BT474 and SKBR3) and triple negative (TN: MDA-MB-468, MDA-MB-231 and BT549)." (PMID 34390568, 2021). "In line with a previous study, our results also suggest that the BCT score can predict whether patients with HR+/HER2− early breast cancer will benefit from adding chemotherapy to hormone therapy." (PMID 33708625, 2021). "The development of novel treatments that are effective and well-tolerated, and their use in combination with ET as part of a first-line regimen for advanced disease in patients with HR+/HER2− advanced breast cancer, has led to improvements in progression-free survival." (PMID 32894087, 2020). "Recently, treatment with the cyclin-dependent kinase 4/6 (CDK4/6) inhibitor palbociclib in combination with endocrine therapy (ET) was incorporated in the National Comprehensive Cancer Network treatment guidelines for patients with HR+/HER2− advanced breast cancer (ABC)." (PMID 32683565, 2020). "Bone is the most common site of metastasis in patients with HR+/HER2− advanced breast cancer." (PMID 32894087, 2020). "Palbociclib is a cyclin-dependent kinase 4/6 (CDK4/6) inhibitor, approved in combination with endocrine therapy for the treatment of women and men with hormone receptor–positive, human epidermal growth factor receptor 2–negative advanced breast cancer (HR+/HER2− ABC)." (PMID 32683565, 2020). "The 4th European School of Oncology–European Society for Medical Oncology (ESO–ESMO) international consensus guidelines for advanced breast cancer recommend endocrine therapy (ET)-based regimens as the preferred first-line treatment option for women with HR+/HER− advanced breast cancer." (PMID 32894087, 2020). "Although all patients had HR+/HER2− advanced breast cancer and were receiving an initial ET-based regimen for advanced disease, the mean duration of this treatment was only 6.7 months, and this short follow-up time must be considered when interpreting the results." (PMID 32894087, 2020). "Moreover, ongoing phase II-IV clinical trials such as PALINA, NCT02600923, NCT02679755 and NCT03633331 are exploring the most frequent adverse effects resulting from the application of Palbociclib in HR+/HER2- advanced breast cancer patients." (PMID 31777590, 2019).